LEP (leptin)
Diseases named in the same sentence as LEP in open-access papers (continued):
Sharing a sentence is not in itself a finding about the gene and the disease.
Obesity (continued). "It is assumed that the anti-obesity effect of leptin is mainly exerted via the brain, especially the hypothalamus." (PMID 37661748, 2023). "Another key player involved in obesity-related hypogonadism is leptin, an adipokine predominantly secreted by white adipocytes and involved in promotion of satiety and energy expenditure." (PMID 37629396, 2023). "The process of leptin resistance, occurring in obesity, plays the key role in complications connected with its course." (PMID 37109160, 2023). "Since leptin reflects fat mass and mouse models of diet-induced obesity usually retain central sensitivity to the long-term anorectic actions of leptin, it is possible that central leptin signaling in Slc12a2βKO mice remains intact as well." (PMID 37819196, 2023). "Leptin, the product of the obese (ob) gene, is a key adipocyte-secreted hormone for energy balance, and is involved in obesity development." (PMID 37894869, 2023). "One possible explanation for these negative results is a redundancy in signaling pathways downstream of leptin as well as other nutritionally regulated hormones that are increased in the setting of obesity." (PMID 37276236, 2023). "Contribution of Slug-based epigenetic reprogramming of leptin pathways to obesity needs to be quantified." (PMID 36512408, 2023). "The concentrations of LEP and ADP in serum were measured, and the association of these two cytokines with different obesity phenotypes were subsequently analyzed." (PMID 37853077, 2023). "In obesity, adipose tissue secretes various adipokines, including leptin and adiponectin, as well as pro-inflammatory cytokines." (PMID 37703108, 2023). "Thyroid hormone excess secondary to global type 3 deiodinase (DIO3) deficiency leads to increased locomotor activity and reduced adiposity, but also to concurrent alterations in parameters of the leptin–melanocortin system that would predict obesity." (PMID 36581316, 2023). "According to the study by Essex and Mosawy (2014), the consumption of green tea decreases obesity by lowering leptin levels and via its effect on the hypothalamus, which is in agreement with our study." (PMID 37512578, 2023). "We have studied two mouse models of obesity, obesity due to an HFD and obesity due to deficiency in leptin (Lepob/ob; ob/ob), a hormone that is produced in adipose tissue and is involved in regulating energy expenditure and food intake." (PMID 37146972, 2023). "Similar profiles are observed in human, rat, and mouse obesity models in which decreased leptin expression is a result of increased adipose Ob mRNA and serum leptin levels." (PMID 37370490, 2023). "The results of this study confirmed the effectiveness of aerobic exercise in controlling obesity by reducing stress, promoting lipid metabolism, and lowering leptin concentrations." (PMID 36833092, 2023). "The pathogenesis of obesity-related hypertension includes insulin resistance, increased leptin levels, increased SNS activity, increased RAAS activity, and impaired salt sensitivity." (PMID 36766978, 2023). "In this paper, we concentrated mainly on the action of adiponectin and leptin in linking obesity with cognitive decline." (PMID 37363537, 2023). "The relationship between airway responsiveness and leptin expression has been reported, and leptin plays an important role in obesity-related asthma." (PMID 38292857, 2023). "The migration of macrophages is stimulated in response to increased leptin levels, which were significantly higher in males with obesity in comparison to females." (PMID 37629396, 2023). "Conversely, hypothalamic LepRb+ neuron–specific overexpression of Slug, mediated by AAV-hSyn-DIO-Slug transduction, induced leptin resistance, obesity, and metabolic disorders in mice on a chow diet." (PMID 36512408, 2023). "Leptin (obesity hormone) is related to obesity-related stimuli, which can be produced by adipose tissue and breast cancer cells." (PMID 37691919, 2023).
Obesity (continued). "The development of IR caused by obesity is connected to the hormones and cytokines produced by adipocytes, including the rise of free fatty acids, TNF, leptin, resistin, and the inadequacy of adiponectin." (PMID 38045856, 2023). "Cinnamon enhances leptin levels, improving metabolism, reducing obesity, and decreasing appetite (Friedman, 2011 ▶)." (PMID 38089418, 2023). "It assesses that tissues have decreased sensitivity to leptin, so higher leptin levels are essential to correct the metabolic imbalance in obesity." (PMID 37960185, 2023). "This relation can be explained in terms of connections between obesity, leptin and the level of SERBP1 expression." (PMID 37240062, 2023). "The metabolic abnormalities connected with obesity can lead to the development of pathophysiological common conditions in humans, such as metabolic syndrome and insulin and leptin resistance (pathological status)." (PMID 38089973, 2023). "Among the various biomarkers related to obesity and MetS, adiponectin, leptin, C-reactive protein (CRP), and cytokines such as interleukins (ILs) -1 and -6 stand out." (PMID 37571250, 2023). "Direct mechanisms tying obesity-driven increases in adipose tissue to tumor cell proliferation and survival through secretion of cytokines such as leptin and IL-6, or to myeloma cell drug resistance are being unveiled." (PMID 36909335, 2023). "Another significant characteristic feature of obesity is high circulating levels of leptin, a phenomenon termed hyperleptinaemia." (PMID 37603580, 2023). "Conversely, the length of cilia is reduced under conditions of low leptin or leptin insensitivity such as diet-induced obesity, ob/ob and db/db mice, or after 36 h of fasting." (PMID 37064917, 2023). "In obese patients, we observed that INSL5 plasma levels showed a strong positive correlation between classic markers of obesity such as BMI, fat mass, and leptin plasma levels." (PMID 37297947, 2023). "Given that treating obesity with leptin is ineffective due to leptin resistance, it seems unlikely that AD will respond to leptin therapy as leptin resistance is thought to be an important factor in this disorder." (PMID 36674935, 2023). "In previous studies, metformin and G. uralensis Fischer improved obesity-related inflammation by decreasing leptin and increasing adiponectin levels, respectively." (PMID 36674447, 2023). "Some studies have suggested a role for adiponectin and leptin from adipocytes in mediating obesity and BE." (PMID 37685616, 2023). "The same improved glucose tolerance with increased GLP-1 and leptin levels was found in DPPIV-depleted Dark Agouti rats with diet-induced obesity." (PMID 37175192, 2023). "During obesity, which is an irregular state of chronic low-grade systemic inflammation, the production and secretion of the most well-known adipokines, leptin and adiponectin, are disrupted." (PMID 37686525, 2023). "Leptin is an anti-obesity hormone which comes from fat that represses appetite and increases energy consumption via its action on the hypothalamus." (PMID 38084147, 2023). "Since the male PE offspring showed an increased postnatal weight gain, a subset of metabolic active obesity-related hormones, such as Ghrelin, Glucagon, Insulin, Leptin and PYY, were analyzed." (PMID 37108049, 2023). "SH2B1 mutant mice present hyperphagia, insulin resistance, and obesity, and hypothalamic overexpression of this protein increases leptin-signaling pathway activity that protects against high-fat-diet-induced obesity and metabolic syndromes." (PMID 36674935, 2023). "For example, genetic impairment of the leptin-melanocortin pathway can result in rare cases of severe early-onset obesity." (PMID 38174068, 2023). "In some individuals with obesity, the brain has difficulty responding to leptin, so plasma leptin concentrations will continue to be produced; this is known as leptin resistance." (PMID 37104164, 2023).
Obesity (continued). "The cytokines IL-6, TNF-α, and leptin play critical roles in the development of obesity, insulin resistance, and chronic inflammation, which culminate into obesity-related metS." (PMID 36982743, 2023). "Associations of rs10487505 with circulating leptin, LEP mRNA and obesity-related parameters were assessed in a linear regression model." (PMID 36833305, 2023). "CB1R-KO mice are also resistant to obesity-accompanied changes in metabolic parameters, including hyperlipidemia and elevated plasma insulin and leptin levels that consequently appear in obese wild-type (WT) mice." (PMID 36830844, 2023). "In leptin-deficient mice, insufficient activation of AMPK, the molecular target of metformin, promotes insulin resistance and obesity." (PMID 36737598, 2023). "Autophagy seems to be involved in leptin resistance as hypothalamic ablation of autophagy-related protein 7 augmented food intake, generating leptin resistance and obesity." (PMID 36674935, 2023). "In particular, promising data revealed that fibroblast growth factor (FGF)-19, FGF-21 and leptin offer great potential for future clinical application in the treatment of obesity and related comorbidities." (PMID 37239098, 2023). "Taken together, the results of recent studies show immense research potential for the clinical use of leptin in the treatment of obesity." (PMID 37239098, 2023). "In the context of obesity, it has been shown that leptin stimulates the production of TNF-α in the human placenta." (PMID 37497352, 2023). "PTP1B is a natural negative regulator of leptin signaling and is overexpressed in diet-induced obesity models." (PMID 37383489, 2023). "The researchers found that the obesity-induced upregulation of PD-1 expression is related to leptin." (PMID 37872469, 2023). "In the case of obesity, there is an infiltration of immune cells into the adipose tissues, with resultant leptin and insulin resistance." (PMID 37892764, 2023). "Leptin is considered as a mediator of the adaptation to fasting and an anti-obesity hormone, whose plasma levels correlate with fat stores and respond to changes in energy balance." (PMID 36836789, 2023). "Epidemiological and clinical data recognize the adipocyte secreted hormone leptin as one of the most important mediators of the link between obesity and cancer." (PMID 37509120, 2023). "Leptin concentrations decreased following most surgeries, possibly because of the correction to leptin resistance that is increased in obesity." (PMID 38116338, 2023). "Administration of an inverse CB1 receptor agonist restores leptin sensitivity and as, shown in mouse studies, has an anti-obesity effect." (PMID 37510734, 2023). "We elucidate that the airway metabolomic milieu is perturbed in obesity and that concentrations of prototypical adipokines, including leptin, are altered." (PMID 37857661, 2023). "Plasma leptin levels had a positive correlation with some clinical parameters of MetS, including obesity (BMI and WHR), HbA1c levels, and insulin resistance (insulin level, HOMA-IR index) but were not related to hypertension, hyperglycemia, and dyslipidemia." (PMID 37703108, 2023). "In this regard, leptin has been widely used as an early predictive marker for obesity and metabolic syndrome since its involvement in early programing." (PMID 36986066, 2023). "Obesity increases leptin levels and reduces adiponectin production, activating the renin–angiotensin system and inflammatory pathways such as TNF-α and NF-KB." (PMID 36830844, 2023). "In contrast, doenjang significantly improved those indicators but also the mRNA levels of leptin and adiponectin in HD-induced obese rats, suggesting the anti-obesity effects of doenjang against HD-induced obesity." (PMID 37862361, 2023). "Butyrate, similar to propionate, has the ability to reduce obesity by stimulating the release of appetite-suppressing hormones and promoting the synthesis of leptin." (PMID 38132864, 2023).
Obesity (continued). "The hypertrophy and hyperplasia of adipocytes are hallmarks of obesity, leading to increased leptin and decreased adiponectin secretion." (PMID 37691744, 2023). "The patho-physiology creates one vicious cycle leading to another, with obesity leading to chronic low-grade inflammation, enhancing gutmicrobiota dysbiosis, insulin and leptin resistance." (PMID 37795371, 2023). "In pathological conditions such as obesity and MetS, several circulating factors such as leptin can directly interact with vascular cells to induce a change in cell phenotype and damage by a mechanism that involves ROS generation." (PMID 36978976, 2023). "Leptin has been shown to successfully lower food intake and body weight and was first considered to be beneficial in the treatment of obesity." (PMID 36790719, 2023). "There is a strong possibility of using leptin as a treatment for overweight and high overweight, obesity and OW/obesity-related disorders." (PMID 37240998, 2023). "The link of circulating IL-6, CRP and leptin with obesity and metabolic abnormalities is well documented, with studies showing their positive association with different anthropometric parameters." (PMID 37529617, 2023). "Loss of Gsα in the DMH of mice impairs leptin signaling, increases food intake and decreases energy expenditure, suggesting that the anti-obesity effects of leptin are at least partially mediated by Gsα." (PMID 38027481, 2023). "Controlling leptin levels by COBLL1 gene expression contributes to the influence of a HF diet in obesity." (PMID 36835164, 2023). "Deletion of SRC-1 in mice impairs hypothalamic leptin signaling, leading to hyperphagia and obesity induced by high-fat diet." (PMID 38027481, 2023). "It is very well known that the accumulation of AT in obesity is characterized by changes in the circulating levels of various adipokines, such as leptin and adiponectin." (PMID 36986134, 2023). "In contrast to leptin, adiponectin levels are decreased in subjects with impaired lung function and obesity." (PMID 38001499, 2023). "Obesity not only increases white adipose tissue, but also alters the adipocyte endocrine function: reducing adiponectin synthesis and increasing leptin production." (PMID 37364149, 2023). "Of note, selective deletion of LepR in LH neurons in adult mice causes obesity only under HFD conditions, reinforcing the notion that the primary target of leptin is context-dependent." (PMID 37547309, 2023). "In contrast to adiponectin, the leptin concentration increases in obesity and insulin resistance due to increased adipose tissue mass." (PMID 37998747, 2023). "Adiponectin, leptin, IL-6, TNF-α and MCP-1 plasma levels were measured by enzyme-linked immuno assays for 60 subjects with FPLD2 and for 60 subjects with obesity." (PMID 37081489, 2023). "It has been observed that obesity-related increases in circulating leptin activate hypothalamic Kiss 1 expression, which regulates GnRH pulse production and puberty onset." (PMID 36947549, 2023). "The obesity-associated inflammatory cytokines, TNF-α, INF-γ, and leptin, increase VEGF-A levels and affect angiogenesis in MDA-MB-231 cells." (PMID 36880535, 2023). "A common finding of obesity is the presence of a metabolic state referred to as “leptin resistance”." (PMID 37892180, 2023). "By discriminant analysis, the combination of follicle-stimulating hormone and leptin was found to be an independent predictor of obesity in pre- and postmenopausal women." (PMID 37371675, 2023). "Low levels of adiponectin are expressed in enhanced adiposity, while those of resistin and leptin have been found to be increased in obesity." (PMID 37371984, 2023). "While leptin promotes osteogenesis by BM-MSC in under basal conditions, long-term exposure to high concentrations of leptin, which occurs in obesity, causes an abnormal leptin response leading to impaired osteoblast differentiation." (PMID 36750692, 2023).
Obesity (continued). "Leptin, reactive oxygen species (ROS), and other adipokines are significantly altered in obesity, contributing to the dysregulation of the HPO axis." (PMID 38264286, 2023). "Children with obesity and asthma had the highest levels of leptin, IL-2 and INF-γ, as well as the lowest level of adiponectin compared to the other groups." (PMID 36767041, 2023). "Obesity damages leptin-induced regulation of BDNF expression and synaptogenesis, which is thought to be related to the onset of depression." (PMID 37387537, 2023). "Since obesity is related to decreased levels of adiponectin and, in turn, to increased levels of leptin, the adiponectin/leptin (A/L) ratio has emerged as a biomarker of AT dysfunction." (PMID 37049561, 2023). "Leptin is increased in obesity, MAFLD and HCC and acts as a mitogen which stimulates cellular proliferation and is associated with carcinogenesis in obesity." (PMID 37470858, 2023). "Obesity is commonly the outcome, which reduces the efficiency of exogenous leptin as a therapeutic agent." (PMID 36790719, 2023). "Obesity related increase in plasma leptin concentration is assumed to induce unfavorable cardiovascular changes via the activation of the sympathetic nervous system and RAAS, leading to hypertension and increased large arterial stiffness." (PMID 36973671, 2023). "Leptin prevents obesity by reducing hunger, promoting satiety, increasing insulin sensitivity and lipolysis, whereas, it protects against cognitive decline by preventing neurodegeneration and obesity-induced leptin resistance." (PMID 37363537, 2023). "In mice, celastrol showed obesity-controlling effects by inhibiting negative regulators of leptin, and reduced obesity-induced OS by increasing antioxidant enzymes and inhibiting NADH oxidase and ROS." (PMID 36978994, 2023). "Deletion of ROCK1 in the ARH results in impaired leptin sensitivity, increased food intake, and severe obesity, highlighting ROCK1 as a critical modulator of leptin’s action on energy homeostasis." (PMID 38027481, 2023). "Individuals with obesity also exhibited elevated levels of leptin, C-reactive protein, insulin, and HOMA-IR index." (PMID 37049393, 2023). "Serum leptin levels increase with obesity and are strongly correlated with fat mass and body mass index (BMI)." (PMID 37593311, 2023). "Adiponectin levels reduce in increased adiposity conditions, and those of leptin increase in obesity." (PMID 37175792, 2023). "As leptin is a potential biomarker of obesity, an interplay between leptin and other biomarkers can be considered." (PMID 36520252, 2023). "ReVgatKOGlp1r mice phenocopied the hyperphagic obesity of KO mice, abrogating the restoration of food intake control, body weight, adiposity, and leptin that was observed in ReVgat mice." (PMID 37581939, 2023). "Given that the cerebellum is responsive to leptin replacement therapies used in obesity, this raises the interesting possibility that leptin also regulates appetite through its effects on the cerebellum." (PMID 36121552, 2023). "Obesity is characterized by the abnormal deposition of fat in the body, leading to metabolic abnormalities, including fatty liver, elevated plasma insulin/leptin levels, and dyslipidemia." (PMID 36902181, 2023). "Noteworthy, the over-expression of leptin, a major player of obesity-related malignancies, has been found in high-grade breast cancer with poor prognosis." (PMID 37509120, 2023). "Other factors found in human milk that are associated with infant growth and later obesity include human milk oligosaccharides (HMO), long-chain polyunsaturated fatty acids (LCPUFA), and hormones such as leptin, insulin, ghrelin, and adiponectin." (PMID 37475022, 2023). "Important mediators of these processes include Inhibitor of KB kinase-beta, SOSC3, c-Jun N-terminal kinases (JNK) and protein kinase C, which contribute to obesity via leptin resistance in AgRP neurons." (PMID 37571301, 2023).